NRP2 (neuropilin 2)
Diseases named in the same sentence as NRP2 in open-access papers (continued):
Sharing a sentence is not in itself a finding about the gene and the disease.
cancer (continued). "Comparable with CAF-200, NRP2-depleted CAFs tended to lack the ability to facilitate the metastatic colonization of 344SQ cells in a mouse tail vein injection model, indicating that NRP2 is essential for the interaction of CAFs with cancer cells." (PMID 38766528, 2024). "Nrp2 enhances cancer cell survival through the regulation of autophagy and endocytic trafficking, a function distinct from its role as a co-receptor." (PMID 38592275, 2024). "Nrp2 is upregulated by epithelial cells upon neoplastic transformation, where it supports cancer cell survival and metastasis by promoting resistance to systemic treatments, angiogenesis, and lymphangiogenesis." (PMID 38592275, 2024). "In conjunction, TAZ confers stem cell-like properties in cancer cells following VEGF/Nrp2-mediated activation of Rac1." (PMID 38592275, 2024). "Through interactions with VEGF-A and VEGF-C, Nrp2 contributes to the aggressive nature of cancer cells." (PMID 38592275, 2024). "Under hypoxic conditions, cancer cells downregulate transcription of Nrp2, preventing antitumor effects of Sema3F." (PMID 38592275, 2024). "Antibody-mediated blocking of Nrp2 inhibits CD44+ CD24Low cancer stem cells and reduces expression of ZEB1, a master regulator of EMT." (PMID 38592275, 2024). "VEGF-A stimulated the migration of CAFs and cancer cells, which was blocked by an NRP2 blocking antibody and Nrp2 siRNAs." (PMID 38766528, 2024). "NRP2 is a single-pass transmembrane protein that is highly expressed in aggressive cancers, especially TNBC." (PMID 39352757, 2024). "The knockdown of Flt1 and Kdr in LFs resulted in a decrease in cancer cell migration and invasion enhanced by NRP2, indicating the essential role of VEGFR1 and VEGFR2 in the NRP2-mediated regulation of CAF activation." (PMID 38766528, 2024). "Nrp2 is preferentially expressed on cancer stem cells capable of initiating tumors where it activates α6β1 integrin expression." (PMID 38592275, 2024). "Here, VEGF/Nrp2 signaling contributes to PD-L1 expression on cancer cells through the activation of the guanosine triphosphatase (GTPase) Rac1 and the transcriptional coactivators YAP/TAZ." (PMID 38592275, 2024). "Nrp2 knockdown by small interfering RNAs (siRNAs) decreased the capacity of CAFs to promote cancer cell invasion and migration." (PMID 38766528, 2024). "For lymphoid immune cells, the expression of NRP1 was negatively correlated with the infiltration of B and T helper (Th) 1 cells, CD4+T central memory (Tcm), and NKT cells in almost all cancers, and NRP2 presented similar results." (PMID 37190154, 2023). "We found that the γH2AX was patently lower in cancer cells cultured by NRP2-nc CAF-CM than NRP2-sh CAF-CM." (PMID 34826008, 2022). "Then, we knocked down the NRP2 in CAFs and found that the effect of protecting cancer cells from chemotherapy diminished." (PMID 34826008, 2022). "Although the NRP-1 importance in cancer has been well-known, the precise role of NRP-2 in oncogenesis has just lately been investigated." (PMID 35052853, 2022). "In the present study, the expression of YAP/TAZ was decreased when cancer cells are cultured by NRP2-sh CAF-CM compared with control cells." (PMID 34826008, 2022). "The secretion of SDF-1 that mediated by VEGF/NRP2 signaling in CAFs and the activation of Hippo pathway in cancer cells in large part participated in this project." (PMID 34826008, 2022). "The presence of NRP-2 appears to be connected to the epithelial–mesenchymal transition’s function in cancer dissemination and metastatic evolution." (PMID 35052853, 2022). "NRP-2 has been shown to grant cancer cells a fibroblastic morphology, which suggests its involvement in the process of EMT." (PMID 35052853, 2022).
cancer (continued). "Neuropilin-2 and TGF-1 signaling work together to promote cancer development, and NRP-2 is involved in the transition from epithelial to mesenchymal cells." (PMID 35052853, 2022). "And, we were given a hint that DNA damage repair enhanced in these cancer cells on account of the normal expression of NRP2 in CAFs." (PMID 34826008, 2022). "According to immunofluorescence examination of several cancer cell lines and tumoral tissues, NRP-2 is expressed on the multiple human CRC cell lines membranes, but not in normal tissues." (PMID 35052853, 2022). "This objective is of major importance considering the possibilities that NRP-2 to become a potential therapeutic target in CRC or other cancers where it is expressed." (PMID 35052853, 2022). "Our study thus eludicated the overall effect of targeting NRP2 in both cancer cells and osteoclasts in PCa bone metastasis, which can prove to be beneficial in the development of an effective treatment strategy." (PMID 33990538, 2021). "The requirement of NRP2 for PCa growth in bone was tested by implanting shNRP2-expressing LNCaP C4-2B cells in the tibia of immunocompromised mice and then knocking down NRP2 from cancer cells in combination with docetaxel." (PMID 33990538, 2021). "The puzzling results that we obtained in the present and in our previous study, highlight the relative importance of NRP1 or NRP2 signaling depending on the cancer type." (PMID 33461580, 2021). "Associations of NRP2, NRP1 and several NRP ligands (i.e., PDGFC and PDGFD) that have been implicated in cancer progression were analyzed." (PMID 33918816, 2021). "Here, we report that targeting NRP2 in cancer cells can enhance taxane-based chemotherapy with a better therapeutic outcome in bone metastasis, implicating NRP2 as a promising therapeutic target." (PMID 33990538, 2021). "As multifunctional membrane proteins, NRP2 enhances or modifies signal transduction pathways through interactions with various receptors or ligands to modulate cancer progression." (PMID 34336654, 2021). "Strongly positive (+++) NRP2 expression was confirmed in 55.36% of PDAC tissues and 17.31% of para-carcinoma tissues, weekly positive (+) NRP2 expression was evaluated in only 14.29% of PDAC tissues and 51.92% of para-carcinoma tissues." (PMID 34336654, 2021). "The NRP2/VEGFC pathway activates autophagy through the inhibition of mTOR complex 1 activity which helps cancer cells to survive following treatment." (PMID 32766254, 2020). "For the correlation with DNAss score, PLXNA1 and A2 showed positive correlation (r = 0.38 and 0.18, respectively), while all other members showed negligible (|r| < 0.17) or insignificant correlation (PLXNA3 and NRP2) across all cancer types." (PMID 32640719, 2020). "When the same analysis was applied to the group of patients, which received radiochemotherapy, NRP2 was highly prognostic for overall and cancer-specific survival." (PMID 32038994, 2019). "NRP2 also regulates the number of EGFR on the surface of cancer cells, thereby controlling EGF-mediated signaling and response to EGFR-targeted therapy." (PMID 30717262, 2019). "We developed a high‐throughput, combined quantitative detection system for Nrp1 and Nrp2 based on liquid chip technology as a potential new method for the early detection, monitoring, and clinical prognosis prediction of cancer." (PMID 30758083, 2019). "We have identified a high correlation of NRP2 and the glioma-associated oncogene family zinc finger 2 (GLI2) transcripts in the cancer genome atlas (TCGA) cohort of BCa patients and a panel of 15 human BCa cell lines." (PMID 32038994, 2019).
cancer (continued). "Other reports describe a lateral interaction of integrin α6β1 with NRP2 on cancer cells and of integrin α5β1 with a VEGFR2-NRP1 complex on ECs." (PMID 30717262, 2019). "NRP2 (neuropilin-2) confers a fibroblastic shape to cancer cells, suggesting an involvement of NRP2 in EMT." (PMID 29258163, 2017). "To further explore clinical relevance of NRP2 expression in human cancer specimen, we analyzed Oncomine Database." (PMID 28796261, 2017). "For example, the two isoforms of NRP2, such as NRP2a and NRP2b, are endowed with opposite role in cancer progression." (PMID 29067024, 2017). "By in situ-PCR, NRP-1 and NRP-2 mRNAs were observed in AMs in lung tissue remote to the cancer nest by coloration with Vulcan fast red stain." (PMID 26900851, 2016). "In this study, we have delineated a novel mechanism for NRP2-mediated regulation of WDFY1 expression in cancer cells." (PMID 27026195, 2016). "Double IHC indicated that 95.8% of DC-SIGN+ AMs co-expressed NRP-1 and 94.9% for NRP-2, in lung tissue adjacent to the cancer margin." (PMID 26900851, 2016). "Regulation of WDFY1 transcription by NRP2 axis is a critical event in maintaining metastatic phenotype in cancer cells." (PMID 27026195, 2016). "It is therefore important to study NRP2 axis in cancer cells, where its function is distinct from its known role in inducing angiogenesis and neurogenesis." (PMID 27026195, 2016). "NRP-1 along with its other family members like NRP-2 is, therefore, considered as a new target for cancer therapy." (PMID 23185562, 2012). "While NRP1 was intensively studied for many years and identified as an attractive angiogenesis target for cancer therapy, the NRP2 signaling pathway has just recently been studied." (PMID 24212788, 2011). "NRP-2 has been detected on the surface of several types of human cancer cells, but its expression and function in gastrointestinal (GI) cancer cells remains to be determined." (PMID 22028766, 2011). "Based on the ability of NRP2 to bind VEGF-A, C and D, studies were conducted to investigate the role of NRP2 in cancer neovascularization." (PMID 21747928, 2011). "Immunohistochemistry studies were then undertaken to determine if NRP2 is expressed at the membrane of various paraffin embedded-human cancer specimen." (PMID 21747928, 2011). "Collectively, these results showed that NRP2 expression in colorectal cell carcinoma promotes cancer cell proliferation and survival." (PMID 21747928, 2011). "To confirm the influence of NRP2 on cell proliferation, we have evaluated in two additional experiments the doubling-times of HT29ctrl, HT29NRP2, Colo320siRNA-ctrl and Colo320siRNA-NRP2 cancer cells." (PMID 21747928, 2011). "Since EMT is a critical step towards invasion and cancer progression, these results suggest that NRP2 fulfills all the criteria of a therapeutic target to disrupt multiple oncogenic functions in solid tumors." (PMID 21747928, 2011). "Although the role of NRP1 in cancer was largely demonstrated, the precise contribution of NRP2 in oncogenesis was only recently considered." (PMID 21747928, 2011). "Our results first confirmed the role of NRP2 in cancer proliferation in vitro and xenograft formation in vivo." (PMID 21747928, 2011). "Immunofluorescence analysis confirmed that NRP2 is expressed at the membrane of several human cancer cell lines." (PMID 21747928, 2011). "Our data support the previous report that downregulation of Nrp2 in cancer cells can lead to fewer metastasis." (PMID 19580679, 2009). "Zhang and colleagues further suggested that VEGF-A may mediate cancer cell stemness via the VEGF/NRP2–Hippo pathway axis." (PMID 41359448, 2026). "This will be important for the target validation with the identification of gene-sets in correlation with NRP1 and NRP2 which can work as biomarkers for cancer diagnosis and prognosis as therapeutic targets to reprogram TAMs and disrupt their pro-tumorigenic functions." (PMID 40134439, 2025).
cancer (continued). "Furthermore, distinctive mRNA expression patterns for NRP1 and NRP2 were noted across the 19 distinct cancer types." (PMID 40134439, 2025). "Hence, we surmised that these two growth factors are interactive mediators between CAFs and cancer cells controlled by the miR-200 and NRP2 axis." (PMID 38766528, 2024). "Further details of the role of Nrp2 in cancer have been described in other malignancies." (PMID 38592275, 2024). "In addition, the NRP2-blocking antibody prevented CAFs from promoting cancer cell invasion and migration." (PMID 38766528, 2024). "Interestingly, our study suggests that the expression of both NRP1 and NRP2 is negatively correlated with the infiltration of these cells in almost all cancers." (PMID 37190154, 2023). "As a non-tyrosine kinase receptor, NRP2 is frequently overexpressed in various malignancies, and associated with many pro-cancer behaviors." (PMID 36172369, 2022). "NRP2 also plays a vital role in cancer cell chemoresistance." (PMID 34826008, 2022). "As has been reported, NRP2 participates in cancer cell metastasis via lymphatic invasion, and blocking NRP2 could repress metastasis." (PMID 34826008, 2022). "Emerging studies suggested that the NRP2/WDFY1 axis was required to maintain endocytic activity in cancer cells, and therefore, therapeutic targeting of endocytosis may be an attractive strategy to selectively target cancer cells in a variety of malignancies." (PMID 36172369, 2022). "Nrp2 has been reported to regulate epidermal growth factor receptor (EGFR) levels in cancer cells." (PMID 35158941, 2022). "Recent studies have demonstrated that the important role of NRP2 in cancer progression and metastases might qualify this transmembrane receptor as a potential therapeutic target." (PMID 33918816, 2021). "In previous studies, the cellular functions of NRP2 have been disclosed in various cancers." (PMID 34516335, 2021). "Moreover, NRP2 and FGFR1 expressions were explicitly associated with cancer survival in bladder cancer." (PMID 32695477, 2020). "NRP2 contributes to laryngeal squamous cell carcinoma progression and could serve as a new therapeutic target for this type of cancer." (PMID 32766254, 2020). "Among these genes, 18 cancer driver genes showed a dual role associated with epigenetic changes, five of which were considered to be critical: SLC27A6, PDGFRA, GAS7, PLXNC1, and NRP2." (PMID 31900418, 2020). "It has been reported that NRP2 and miR-146a are related to cancer metastasis." (PMID 33396906, 2020). "In cancer cells, the expression of NRP2 is negatively correlated with WDFY1." (PMID 32104603, 2020). "In the same line of evidence, the VEGF-C/NRP2 axis (through the inhibition of mTOR complex 1) was found to protect prostate and pancreatic cancer cells during chemotherapeutic stress, by activating autophagy to support cancer cell survival." (PMID 31027288, 2019). "Moreover, it was already shown that NRP2 and E-Cadherin expression are connected in multiple cancer types." (PMID 32038994, 2019). "Concerning NRP2, it is of particular interest that a recent work reported that an acquired resistance to MET oncogene-targeted drugs is associated with NRP2 loss in diverse cancer cell models." (PMID 31027288, 2019). "Since the importance of microRNAs has been well documented in cancers and we were interested in the identification of possible networks connecting Vegfa and/or Nrp2 with the EMT phenomenon in SHH MB CSC, we extended the analysis to the EMT related microRNAs deregulated between SHH MB CSC and NSC." (PMID 30483126, 2018). "That NRP2 clearly has a role in maintaining normal bone health may provide a target for the treatment of cancers that metastasize to bone." (PMID 29067024, 2017). "Besides being found in vascular and lymphatic channels, NRP1 and NRP2 are also expressed in a wide variety of human cancers, such as lung, breast, prostate, colon, pancreas, neuroblastoma, melanoma, etc.." (PMID 25890345, 2015).
cancer (continued). "Moreover, neuropilin-2 conferred a fibroblastic-like shape to cancer cells, suggesting an involvement of neuropilin-2 in epithelial-mesenchymal transition." (PMID 21747928, 2011). "Moreover, NRP2 confered a fibroblastic-like shape to cancer cells, suggesting an involvement of neuropilin-2 in epithelial mesenchymal transition (EMT)." (PMID 24212788, 2011). "The precise role of NRP2 on cancer progression was first characterized in vivo." (PMID 21747928, 2011). "SB-431542 treatment decreased dose-dependently vimentin expression in Colo320 and HT29NRP2 cancer cells and even restored E-Cadherin levels in HT29NRP2 underlying that TGFRI plays an essential role in the maintenance of the EMT phenotype conferred by NRP2." (PMID 21747928, 2011). "We first sought to examine the expression of NRP2 glycoprotein in various cancer cell lines." (PMID 21747928, 2011). "A549 and ACHN carcinoma cells also expressed NRP2 at a level similar to that of NRP1." (PMID 20087344, 2010). "In normal and cancer tissue, Nrp2 expression was identified in blood or lymph vessels." (PMID 19580679, 2009). "Moreover, NRP2/WDFY1 axis plays an important role in cancer cell endocytosis." (PMID 32104603, 2020). "However, a deeper understanding is needed to elucidate the effect of NRP1 and NRP2 on cancer cells." (PMID 30871059, 2019). "The NRP2/WDFY1 axis may regulate cellular functions beyond cancer cells." (PMID 27026195, 2016). "Amongst the 19 cancer cell types, ccRCC cases showed the highest mRNA of NRP1, while NRP2 was mostly expressed in SKCM samples." (PMID 40134439, 2025). "In response to cancer-cell-secreted Sonic Hedgehog (SHH), Nrp2-mediated signaling promotes an immunosuppressive (alternatively activated) polarization of TAMs through the transcription factor Krüppel-like factor 4 (Klf4)." (PMID 38592275, 2024). "NRP2-VEGFR signaling facilitates the secretion of VEGF-D and pleiotrophin from CAFs, leading to the activation of cancer cell migration and invasion." (PMID 38766528, 2024). "CAF has been demonstrated to confer 5-fluorouracil (5-FU) resistance to GC cells by expressing neuropilin 2 (NRP2), eventually activating the Hippo pathway and alternatively activating JAK/STAT3 in cancer cells via secreting cytokines." (PMID 37784082, 2023). "When SIX1 is expressed in EMT cancer cells, VEGF-C is activated, and through neuropilin 2 (NRP2)/Fms-related tyrosine kinase 4 (FLT4), GLI signals in adjacent epithelial cancer cells are activated." (PMID 36624542, 2023). "Angiogenesis inhibitors, such as bevacizumab, can face resistance from cancer cells that involves alteration of VEGF tyrosine kinase receptors (VEGFR) and binding with Neuropilin-1 (NP1) and/or Neuropilin-2 (NP2)." (PMID 35163777, 2022). "In vitro work using CRC cell lines has shown that Nrp2 can induce proliferation and EMT by cooperating with the TGFβ1 receptor, and restrict apoptosis to promote cancer progression." (PMID 35158941, 2022). "The result showed TAMs would receive activated signals from cancer cells through GAS6-AXL, RPS19-C5AR1, FAM3C-LAMP1, CD47-SIRPA, and VEGFA-NRP1/NRP2 L–R pairs in TME." (PMID 34676217, 2021). "For immune score, PLXND1 showed the highest correlation (r = 0.46) across all cancer types, followed by PLXNC1 (r = 0.39), NRP1 (r = 0.23) and NRP2 (r = 0.15) (p < 0.0001)." (PMID 32640719, 2020). "All six selected survival-related genes (EMP1, TPM1, NRP2, FGFR1, CAVIN1, and LATS2) were reported to play a positive role in disseminating cancer cells or invasion in many kinds of cancers." (PMID 32695477, 2020). "For stromal score, NRP1 showed the highest positive correlation across all cancer types (r = 0.59), followed by PLXND1 (r = 0.54), NRP2 (r = 0.50), PLXNC1 (r = 0.48) and PLXNA4 (r = 0.28) (p < 0.0001)." (PMID 32640719, 2020). "Recently, it was demonstrated that NRP2 regulates mTOR signaling, β-catenin signaling, endosome maturation, and EGFR trafficking sustaining cancer development." (PMID 28804523, 2017).